CD4 (CD4 molecule)
Diseases named in the same sentence as CD4 in open-access papers (continued):
Sharing a sentence is not in itself a finding about the gene and the disease.
tumor (continued). "The congenital deficiency of CD11chi DCs not only reduced the expression of CD44 on CD4+ T cells and CD8+ T cells in lymphoid tissues under homeostatic and tumor-bearing conditions but also enhanced their expressions of several immune checkpoint molecules under tumor-bearing conditions." (PMID 39206204, 2024). "In an independent study, eliminating CD4+ T cells or NK1.1+ NK cells individually did not impair tumor response to DCP-IL-12/FLT3L treatment, and disrupting CD4+ T cells was associated with compensatory increases in both total and activated (IFNγ+ or GZMB+) CD8+ T cells." (PMID 37996514, 2024). "Additionally, we found increased expression of the CXCL13 program in CD4+ resident memory and CD8+ exhausted subsets, which may be consistent with the expansion of tumor-reactive CD8+ T cells." (PMID 39417106, 2024). "In addition to priming CD4+ T cells by peptide-MHC II complex, these tumour antigen-loaded DCs also elicit effective CD8+ T-cell anti-tumour response through cross-priming, a process in which DC presents the exogenous peptide by MHC I molecules to prime CD8+ T cells." (PMID 38183840, 2024). "Furthermore, the author, by using a TNBC NOS-2− murine model, demonstrated that treatment with indomethacin, a NSAID, increased the intratumor level of both CD4+ and CD8+ T cells relative to untreated controls, and, in particular, a marked concentration of CD8+ T cells in the tumor core." (PMID 38892411, 2024). "Additionally, tumor-derived components contribute to the creation of an immunosuppressive microenvironment by promoting the secretion of VEGF in Monocytes, Tregs, B cells and CD4 T naïve cells." (PMID 38348038, 2024). "Disruption of ZFP36 in CD4 mesoCAR-T cells cocultured with antigen-negative tumor cells led to a statistically significant, slight increase in CD25+ CD69+ population; however, this difference was notable only in one of three donors and is not a strong phenotypic difference." (PMID 38326511, 2024). "However, CD4+ regulatory T cells can suppress immune function, leading to IL-2 depletion, reducing CD8+ T cell infiltration and activity in tumor tissues, thus facilitating tumor cell immune escape." (PMID 38312647, 2024). "Using flow cytometry and bulk-RNA sequencing, we probe the immunological mechanism of this synergy and find that CD4+ T cell depletion leads to an enhanced activation state in the tumor draining lymph node (TdLN), generating an influx of newly primed CD8+ T cells into the tumor." (PMID 38429261, 2024). "Furthermore, HPV+ tumor cells could directly induce CXCL13 expression in CD4+T cells, differentiating CXCL13+CD4+T cells, as evident in our co-culture assays." (PMID 39105803, 2024). "In solid tumors of nonlymphoid origin, Tregs may constitute 30–45% of CD4+ T cells, depending on the tumor type, and can also hinder the success of α-PD1 cancer immunotherapy." (PMID 39050547, 2024). "This retrospective study compared the density of CD4 + and CD8 + T cells in the peritumoral and intratumoral area of patients with NSCLC operated with and without neoadjuvant treatment, and their relationships with each other according to tumor subtype and tumor stage." (PMID 38468248, 2024). "HSPs and autologous tumor antigen polypeptides can form complexes, named HSP-peptide complexes (HSPPCs), to mediate cell endocytosis and antigen presentation by binding to APC membrane receptors, activating CD4+ and CD8+ T cells and triggering immune responses against tumor antigen peptides." (PMID 39406966, 2024). "This is important because HDVax-induced inhibitory Tr1 cells and effector LDVax-induced helper CD4+ T express similar levels of CD39, suggesting that other factors beyond CD39 are required to differentiate between CD4+ T cells that inhibit versus promote tumour rejection." (PMID 39048822, 2024).
tumor (continued). "Another limitation has been already mentioned: the evaluation of mechanistic pathways (including mRNA cytokine expression, CD4/CD8 circulating and tumor levels, among others) could provide additional, valuable information about real nutritional-related modulation." (PMID 38892006, 2024). "Comparison of the immune cell depletion curves to the no treatment control in the same experiment suggests that there was some tumor growth delay even in the 93-100% absence of NK, CD4+ T and/or CD8+ T cells, suggesting that additional mechanisms contribute to tumor growth inhibition." (PMID 39606250, 2024). "It illustrates the interaction between endogenous immune cells (CD4+ T cells, CD8+ T cells, B cells and dendritic cells) and NY‐ESO‐1‐specific T‐cell receptor‐engineered cells (including natural killer cells, CD4+ T cells and CD8+ T cells) in targeting tumours." (PMID 39275923, 2024). "Furthermore, effector immune cells such as natural killer (NK) cells, CD4+ T-cells, and CD8+ T-cells are present and activated in the TME at the early stage of PDAC exerting intricate influences on the tumour behaviour either by fueling its growth or orchestrating its suppression." (PMID 38973003, 2024). "To determine whether the effect is mediated by IL-12, we used flow cytometry and observed that the expression of GSDME in tumor cells did not affect the total number of CD4+ T cells in vitro." (PMID 38169676, 2024). "Additionally, in three mouse tumor models, CD4+ T cells identified the immunogenic mutanome of non-synonymous cancer mutations more often than CD8+ T cells." (PMID 39452154, 2024). "This study considers the possibility that CXCR4-tropic HIV could inhibit tumor-promoting macrophages and the potential for CXCR4-tropic HIV to induce apoptosis in breast cells independently of CD4 interaction, suggesting a unique mechanism by which these HIV variants might reduce BC risk." (PMID 38542195, 2024). "CD4+ helper T cells provide vital signals to conventional CD8+ cytotoxic T cells through mechanisms collectively known as CD4 help, an important function of CD4+ T cells that has emerged as a critical factor involved in promoting strong anti-viral and anti-tumor CD8+ T cell responses." (PMID 38341416, 2024). "Moreover, their levels were relevant also for patient survival, since all these populations correlated with a longer survival except for CD4+ T cells, confirming the primary role of CD137+ T cells, particularly the CD8+ subset in the induction of the anti-tumor immune response." (PMID 38570798, 2024). "Hence maintaining the balance between CD4+ and CD8+ T-cells is critical for tumour immunity." (PMID 38973003, 2024). "Accordingly, the combinatorial treatment resulted in increased proportions of both CD4+ and CD8+ T cells in the tumor mass, where CD8+ T cells also expressed higher levels of the activation marker PD-1 and increased numbers of CD8+ T cells spatially localized in the inner tumor parenchyma." (PMID 38509063, 2024). "Next, to specifically investigate whether I-NCMs can induce tumor lysis independent of T cells, we pharmacologically depleted CD4+ and CD8+ T cells in Nr4a1–/– mice and evaluated the efficacy of I-NCMs." (PMID 39545417, 2024). "It is not known whether such tumour responses involve transfer of tumour antigen to endogenous APCs, nor whether they are driven by CD4+ T cells alone or a combination of CD8+ and CD4+ T cells." (PMID 38125720, 2024). "A simpler method is to prepare tumor vaccines from whole tumor cells which does not require identification of specific antigens and has the advantage of providing multiple antigens to stimulate a robust CD4+ and CD8+ T cell response." (PMID 39152131, 2024). "Increasing proof indicates that within a designated ‘hot’ tumor microenvironment (TME), macrophages tend to discharge the pro-inflammatory and chemokines after engulfing cancer cells, which then allure and exhibit the antigenic signals to activate CD4+ T cells and cytotoxic CD8+ T cells." (PMID 38824567, 2024).
tumor (continued). "The tumor cells typically do not express surface CD4, CD5, CD8, betaF1, or TRC delta." (PMID 38611591, 2024). "Research in cancer immunotherapy has mainly focused on CD8+ T cells in the tumor microenvironment (TME), However, it has been reported that antitumor immunity cannot be induced unless the tumor cells have the MHC class II binding neoantigens, which are recognized by CD4+ T cells." (PMID 39588306, 2024). "No mice from the p15E-3C only group and p15E-3C + CD4 MAb group showed tumor length over 10 mm." (PMID 38506662, 2024). "Flow cytometry analysis revealed a significant increase in the quantity of CD4+ T cells among all the immune cells analyzed in the 4T1-shCCT2 tumors but not in the number of CD8+ T cells, tumor-associated macrophages (TAMs), or myeloid-derived suppressor cells (MDSCs) upon CCT2 suppression." (PMID 39079960, 2024). "Meanwhile, the percentage of CD8+ TCR-T rather than CD4+ TCR-T showed more increase within the tumor in mice receiving IL-21R-TCR-T than conventional TCR-T treatment, demonstrating the superior proliferation and infiltrating capacity of CD8+ IL-21R-TCR-T within the tumor microenvironment." (PMID 38643203, 2024). "As combination therapy could augment different cell types to improve anti-tumor immunity, we characterized CD8+, Tconv (CD4+Foxp3−), Tregs (CD4+Foxp3+), DCs (CD11c+MHC-II+), monocytic (CD11b+Ly6C+/−F480+/−CD64+/−) and neutrophilic (CD11b+Ly6G+) derived myeloid cell populations." (PMID 39343508, 2024). "In preclinical BrCa models, GEM has been deemed a myeloablative therapy, as it significantly reduces the presence of GR-1+ MDSCs in the periphery of tumor-bearing mice without perturbing other immune cell populations like CD4+ T cells, CD8+ T cells, and B cells." (PMID 39195207, 2024). "Although it has been shown that CD4+ T cells specific for tumor antigens can mediate the elimination of tumor cells even in the absence of endogenous expression of MHC class II on tumor cells, the presence of the mature potent DCs is extremely important for their activation." (PMID 38920557, 2024). "Additionally, no statistical alteration was recorded between CD4+T-cells and tumour severity for HIV-positive PDAC patients in this cohort." (PMID 38973003, 2024). "In addition, CD4+ and CD8+ T cells were detected in distant tumor tissues." (PMID 38742454, 2024). "Therefore, increasing collagen production creates a barrier that may reduce immune cells such as CD8+ T cells, CD4+ T cells, and NK cells (CD3− and CD56+) infiltration and tumour immune surveillance." (PMID 39496484, 2024). "In comparison to normal tissues, there was a notable enrichment of naïve CD4+ T cells and regulatory T cells (regs) within the tumour tissues, irrespective of their MPLC or SPLC origin, while NK and CD8+ Teff cells were mainly distributed in adjacent normal tissue." (PMID 39601163, 2024). "This, together with no changes in CD8+ T cell or CD4+ T-cell subset densities between tumor and nontumor regions, suggests that the TME may be skewed by the recruitment of monocytes." (PMID 39761010, 2024). "The superior activation of CD4+ and CD8+ T cells could be induced by a higher frequency of migratory cDC1s (XCR1+ CD103+), which possess the unique ability to transport tumor antigens to lymphoid structures and excel at cross-presenting the TAAs to CD8+ T cells." (PMID 39703517, 2024). "Therefore, an increase in CD8 + T cells proportion and a decrease in CD4 + /CD8 + ratio were observed after NAT among patients with high tumor burden in the non-pCR group." (PMID 38834662, 2024). "Immunohistochemical results showed a significant increase in the infiltration of CD4+ T cells, CD8+ T cells, CD68+ macrophages, and F4/80+ Kuffer cells in tumor tissues, which suggested a high degree of immune infiltration in the tumor tissues of DEN and CCl4-induced HCC mouse models." (PMID 38580754, 2024).
tumor (continued). "Moreover, TNF-α and IFN-γ could induce high levels of CD40 on mature MDSCs through interacting with CD40L on T cells after CTT to promote Th1-dominant CD4+ T cell differentiation and orchestrate CTT-induced long-term anti-tumor immunity." (PMID 38791188, 2024). "By sorting each tumor infiltration cell type, RT-PCR as well as qRT-PCR analysis demonstrated only the whole tumor tissues and CD8 cells had circATXN7 expression, but other components including CD4, macrophages, endothelial cells, and fibroblasts displayed negligible expression of circATXN7." (PMID 38216551, 2024). "Similarly, depletion of NK cells did not affect CRI-induced tumor regression, suggesting that cells other than CD4 or CD8 T cells, or NK cells, were responsible for this early regression of large tumors." (PMID 39076988, 2024). "Such alterations included the significant increase in the effector memory (EM) CD4 T cells in the primary and secondary tumors, and a significant increase of EM CD8 T cells in the secondary tumor, suggesting a heightened presence of T cells primed for immediate immune responses against the tumor." (PMID 39218928, 2024). "Importantly, depletion of CD8+ T-cells, but not CD4+ T-cells abrogated the effect of decreased tumour growth after IAV infection." (PMID 38271469, 2024). "While CD4+ T lymphocyte subpopulations may not share identical roles, they collectively contribute to tumour immunity." (PMID 38894548, 2024). "Flow cytometric analysis of mesenteric lymph nodes (mLN), spleen and tumour revealed that, as previously reported in other cancer models, Salmonella treatment induced high production of IFN-γ across all tissues in CD4 and CD8 T cells compared to the PBS control." (PMID 39558103, 2024). "B cells could promote the formation of immunosuppressive cells by releasing immunosuppressive cytokines, and also participate in the process of presenting tumor antigens to CD4 T and CD8 T cells, directly attacking tumor cells through Granzyme B, and are important anti-tumor cells." (PMID 38773226, 2024). "Increased presence of CD4+ T cells is correlated with better survival in cancer patients, while a higher CD4-to-CD8 ratio of T cells in leukapheresis products used for making CAR T therapies has been shown to improve anti-tumor responses with better clinical outcomes." (PMID 39689157, 2024). "The FMD showed no change in tumor-infiltrating CD4 and CD8 cells in 4T1 cancer cell-bearing mice." (PMID 38999849, 2024). "We have previously demonstrated these in vivo activated B cells express CD19, B220, CD23, HEL+ with subtle upregulation of MHC-II and CD95.4,5 Importantly, no proliferation is observed when naïve 5C.C7 CD4 T cells are transferred into I-E- anti-CD40 activated SWHEL transgenic tumour bearing mice." (PMID 38125720, 2024). "Replacing bone marrow of wild-type mice with bone marrow from ERβ mutant mice led to fewer tumor-infiltrating CD8+ and CD4+ T cells compared to the control mice, indicating the impaired ability of host immune cells to control tumor growth in the absence of ERβ signaling." (PMID 39175529, 2024). "Tryptophan catabolism by IDO1 and TDO2 is critical within the tumour microenvironment (TME) as lowered tryptophan and raised kynurenine each confers an anti-immune response, by attenuating CD8+ Tcell infiltration, and promoting regulatory CD4+ cell differentiation." (PMID 39048947, 2024). "Additionally, the tumor sample contained various other cell types, including epithelial cells (EPCAM+), pStr (MKI67+) CD4+T cells (CD4+), CD8+ T cells (CD8A+), macrophages (CD68+), and regulatory T cells (FOXP3+), which were further validated by our single-cell data." (PMID 39676856, 2024).
tumor (continued). "In addition, we further verified the role played by both CD4+ and CD8+ T cells in anti-tumor response elicited after the vaccination protocol by performing an in vivo depletion experiment, e.g., depleting selectively CD4+ or CD8+ T cells while injecting MOC2-CIITA or parental cells in mice." (PMID 39035008, 2024). "In addition, CD3G+T cells ratio was significantly correlated with CD68 + macrophages, CD4 + T cells, and CD8 +T cells ratio, indicating it could play an important role in the anti-tumor immunity in DLBCL." (PMID 38980810, 2024). "Indeed, a peptide-based VP1 vaccination with the crassocephalum rabens-derived adjuvant CRA could induce VP1-specific CD4+ and CD8+ immune responses mediating an anti-tumor effect." (PMID 38793784, 2024). "In a mouse tumor model, the inhibition of CDK5 expression or the combination of CDK5 inhibition with anti-PD-L1 therapy can significantly inhibit tumor growth and lead to increased levels of CD3+, CD4+, and CD8+ T cells in the spleen and decreased PD-1 expression in the CD4+ T cells." (PMID 38782996, 2024). "Clinical trials almost unanimously point to the activation of both humoral (facilitated by CD4+ T-cells) and cellular immune responses (mostly by the activation of CD8+ T-cells) following DNA vaccination which means many different mechanisms work synergistically to eliminate the tumor." (PMID 39872522, 2024). "Accordingly, we demonstrated previously that the blockage of ILT3 during the priming of T cells by tolerogenic DCs can also block the suppressive properties of IL-10-producing CD4 and CD8 T cells 19, which could be harnessed for the development of tumour therapy." (PMID 38322117, 2024). "Moreover, intraperitoneal injection of the compound in a syngeneic mouse tumor model led to decreased tumor growth in human PD-L-1 transfected murine melanoma and lung cancer, enhanced tumor infiltrating CD8+ cell abundance, and reduced tumor and FoxP3+ CD4+ cell abundance expressing PD-L-1." (PMID 38660299, 2024). "It is noteworthy that we observed a significant increase in the infiltration of CD4 and CD8 lymphocytes in the adjacent normal tissue, which may suggest that immune cells may have infiltrated around the lesions in the early stages of tumor development." (PMID 38370388, 2024). "An analysis of CD4+, CD8+, and OVA-specific CD8+ T cells in the tumor on day 10, but not on day 2 post-treatment start, revealed an increase in numbers in both directly injected and distant tumors in mice treated with VSV-NDV that reached statistical significance for the treated tumor." (PMID 39410025, 2024). "Analysis in CRC also shows a significantly higher frequency of CD4 + Foxp3 + Treg cells and CD68 + CD163 + M2 macrophages in intratumoral TLS compared to peritumoral TLS, suggesting a potential correlation between peri-tumor TLS and the immunosuppressive environment within the tumor." (PMID 39068459, 2024). "However, depletion CD4+ T cells have no obvious effect both in tumor volume and weight in Ogt−/− tumor-bearing mice, compared to the isotype antibody treatment group." (PMID 38168435, 2024). "Upregulation of FCN1 potentially enhances immune cell activation (e.g., CD4 T cells, CD8 T cells, NK cells, Th1 cells, and MDSC) and their infiltration into tumors by modulating the expression of chemokines, their receptors, and cell adhesion molecules in the tumor microenvironment." (PMID 39139822, 2024). "Also, it has been proposed that the amount of CD4+ and CD8+ T‐cells might be too low in the GB tumor microenvironment to result in robust treatment responses to immune checkpoint blockade." (PMID 39618405, 2024). "A trial in rGB patients tested this hypothesis and showed an increase in the mOS, a specific peripheral immune response to the peptides bound to HSPPC-96, a focal cellular infiltrate of CD4+ and CD8+ and, in addition, brain biopsies were consistent with specific immune responses at the tumor site." (PMID 38473776, 2024).